RN7SKP97 (RN7SK pseudogene 97)
Gene: Miscellaneous RNA gene on chromosome 8 (61,631,680 to 61,632,012, reverse strand). Ensembl gene ENSG00000222898.
Homologues: Orthologues: chimpanzee 7SK (98% identical). Paralogues in human: RN7SKP90 (71% identical), RN7SKP217 (69% identical), RN7SKP124 (69% identical), RN7SKP203 (69% identical), RN7SKP176 (68% identical), RN7SKP77 (68% identical), RN7SKP162 (68% identical), RN7SKP249 (68% identical), RN7SKP79 (68% identical), 7SK (68% identical), RN7SKP184 (68% identical), RN7SKP230 (68% identical), and 284 more.